CXCR4 (C-X-C motif chemokine receptor 4)
Diseases named in the same sentence as CXCR4 in open-access papers (continued):
Sharing a sentence is not in itself a finding about the gene and the disease.
cancer (continued). "In cancer, MIF predominantly signals through binding with the CD74 receptor, however, binding through the chemokine receptors CXCR2, CXCR4, and CD44 have also been shown." (PMID 32317702, 2020). "CXCR4 belongs to G protein-coupled receptor superfamily, which selectively binds to Stromal cell-derived factor 1 (SDF-1), also known as CXCL12 to promote cancer metastasis." (PMID 30678736, 2019). "In prostate cancer, CXCL12/CXCR4 signaling induces the expression of CD164 and promotes homing of cancer cells to the bone marrow." (PMID 31007847, 2019). "Recent investigations demonstrated that SDF-1 and CCL21 chemokines through their cognate receptors CXCR4 and CCR7, signals to mTOR pathway in other cancers." (PMID 30518812, 2019). "A small cyclic peptide, LY2510924, and an antibody against CXCR4, LY2624587, have been developed to target tumors and cancers." (PMID 30791675, 2019). "GLI1 increases metastatic potential by tuning up the levels of the CXCR4/CXCR7 receptors in BC cells and in other cancers." (PMID 31027259, 2019). "We found that radiation induced the up-regulation of the chemokine CXCL12 and its receptor CXCR4, of the metalloproteinases 9 and 12 (MMP9 and MMP12), and of key transcription factors involved in the expression of genes related to migration of cancer cells." (PMID 30813636, 2019). "Referring to hematological malignancies, some CXCR4 antagonists, like AMD3100 and the derivative AMD3465, enhanced the efficacy of conventional therapies inducing the mobilization of cancer cells from the protective environment of the BM." (PMID 30894861, 2019). "CSC have been isolated from nearly every human cancer through identification of surface marker expression of nearly 40 different markers which vary from cancer to cancer (CD133, CD44, CXCR4, CD90, etc.)." (PMID 32355893, 2019). "Stromal cell-derived factor 1 (SDF1) is a CAF-secreted factor that can activate C-X-C chemokine receptor type 4 (CXCR4) and ultimately stimulates cancer cell proliferation." (PMID 30925923, 2019). "The reduced RhoA activity resulted in increased expression of the cognate receptor, CXCR4, for CXCL12 in 4T1 cancer cells." (PMID 31705019, 2019). "It is therefore likely that the increased co-expression of CXCR4 and CCR5 in RhoA knockdown cancer cells facilitates the recruitment of CXCL12/CCL5 secreting CAFs and later the TAMs into the TME." (PMID 31705019, 2019). "Recently, a number of reports have revealed that heterodimers of CXCR4 and CXCR3 or CXCR7 possess numerous functions, including roles in cancer cell invasion." (PMID 30791675, 2019). "In recent years, many cancer studies have described the crosstalk between the CXCR4/SDF-1 axis and the Akt/mTOR pathway and demonstrated the inhibitory effect of CXCR4 antagonist (AMD3100) on mTOR expression." (PMID 32047724, 2019). "Next-generation sequencing revealed that the CXCR4 expression was significantly higher after the hypoxic condition, which functionally resulted in the EMT and cancer stemness acquisition." (PMID 30760238, 2019). "The most critical impact however is probably related to cancer metastases, since the respective tumor cells apparently hijack the CXCL12-mediated homing to the bone marrow by expressing CXCR4." (PMID 31572390, 2019). "In particular, by administering the culture medium of pancreatic stellate cells (PSCs) to AsPC-1, BxPC3, and SW1990 cancer cells, an increase in proliferation, migration, and invasion due to activation of CXCL12-α/CXCR4 axis was observed." (PMID 31275385, 2019). "The chemokine SDF-1 and its cognate receptor CXCR4 play multiple roles in HCC progression, including promoting angiogenesis, maintaining cancer growth, inducing EMT, facilitating invasion and dissemination, and aiding escape of immune surveillance." (PMID 31151472, 2019). "We quantified by an ELISA-based technique specific proteins of cancer-derived exosomes (CD44,CD44v6,EpCAM,CD9,CD81,Tspan8,Integrin α6,Integrin β4,CD24,CXCR4)." (PMID 31048929, 2019).
cancer (continued). "The interaction between SDF-1 and CXCR4 can be interrupted as well, and targeting CXCR4 has shown to reduce metastasis, as SDF-1/CXCR4 expression and binding induces migration of cancer cells." (PMID 31263976, 2019). "Overall pooled analysis suggests that high expression of CSC markers (including CD133, CD44, CXCR4, and CD105) predicts poor overall survival, cancer-specific survival, disease-free survival, and progression-free survival." (PMID 30796200, 2019). "The activated CAFs release the CXCL12 chemokine, which binds to its two receptors, CXCR4 and ACKR3, highly expressed on the cancer cells surface." (PMID 31275385, 2019). "Numerous clinical studies proved the effectiveness of plerixafor (AMD3100), a CXCR-4 inhibitor as well as CTCE-9908, a CXCL-12 peptide analogue, in cancer treatment." (PMID 28660349, 2018). "The molecules which can block CXCR4 and CXCR7 simultaneously, represent an ideal pharmacological approach because both receptors are involved in cancer malignancy and GBM angiogenesis." (PMID 29977203, 2018). "Migration and invasion of CXCR4+ papillary thyroid carcinoma cells are dependent on CXCL12, which was produced by senescent cancer cells at the invasive border." (PMID 29527513, 2018). "Consistent with the important roles of CXCL12/CXCR4 in cancer, many studies have proven that high levels of CXCL12 and CXCR4 are related to worse prognosis in various malignant tumors." (PMID 30574021, 2018). "Under the influence of CAF-secreted IGF1 and SDF-1 (stromal-derived factor-1) a subpopulation of cancer cells that expressed the IGF1 receptor IGF1R and the SDF-1 receptor CXCR4 outgrew other cancer cell subpopulations." (PMID 29774124, 2018). "CXCR4 plays a central role in the pathogenesis of HIV and several cancers and Nef is a small viral protein produced by HIV to subvert the innate and humoral immune response to optimize conditions for viral replication." (PMID 29682200, 2018). "More importantly, they were resistant to cisplatin, oxaliplatin and cyclophosphamide exhibiting high cross-resistance along with alterations in expression of cancer-stem cell markers such as CD133, CD166, CD24, CD26, CXCR4, CD271 and CD274." (PMID 30143021, 2018). "Remarkably, IL-6, IL-10, CXCR4, and CCL2 mRNA, which are all STAT3 target genes involved in cancer progression, were increased in macrophages exposed to exosomes." (PMID 29867925, 2018). "The remaining two visually undetectable cancers were comprised of TNBC with low and moderate CXCR4 staining intensity respectively in immunohistochemistry." (PMID 30191351, 2018). "Cancer cells induce TGF-β-dependent upregulation of CXCR4 in monocytes, while CXCL12 expressed by perivascular fibroblasts attracts these motile TAMs toward the blood vessels, bringing motile cancer cells with them." (PMID 29719241, 2018). "CXCL12 signals through CXCR4 and CXCR7 receptors upregulated on cancer cells, and activates multiple molecular pathways such as the mitogen-activated protein kinase (MAPK), inositol 1,4,5-triphosphate (IP3), and phosphoinositide 3-kinase (PI3K)." (PMID 29416611, 2018). "KRT19 regulated cancer stem cell reprogramming by modulating the expression of cancer stem cell markers (ALDH1, CXCR4, and CD133), as well as the phosphorylation of Src and GSK3β (Tyr216)." (PMID 29747452, 2018). "TA-1 inhibited the proliferation, invasion, and metastasis of Panc28, Miapaca, and HL60 cancer cells by down-regulating Bcl-xL, XIAP, survivin, MMP-9, and CXCR4 expression." (PMID 30190788, 2018). "Recent studies have proved that the CXCR-4 and its ligand CXCL-12 (SDF-1) are promising targets for cancer therapy." (PMID 28660349, 2018). "PGE2 controls the local recruitment of MDSCs by regulating their expression of CXCL12 and CXCR4 and stimulates tumoral secretion of the pro-angiogenic CXCL1, thus promoting micro-vessel formation and cancer progression." (PMID 30591657, 2018).
cancer (continued). "It is known that the overexpression of ALDH1, CXCR4, and CD133 produces cells with an aggressive and highly drug-resistant cancer stem cell-like phenotype." (PMID 29747452, 2018). "Instead, an increase in Cxcr4 gene expression in PBS group was observed, in accordance with the fact that this chemokine receptor has been shown overexpressed in several human cancers." (PMID 29410666, 2018). "The chemokine CXCL12 and its receptors, CXCR4 and CXCR7, participate in tumorigenesis and metastasis in several types of cancers." (PMID 30591657, 2018). "The knowledge about these functions is indispensable for developing new concepts of anti-cancer therapy that comprise radiotherapy, immunomodulation and SDF-1/CXCR4 targeting." (PMID 30622535, 2018). "Altogether, our findings provide proof for interactions of BK with the purinergic signaling system and also with the CXCR4-SDF-1 axis involved in metastasis, making them attractive targets for development of anti-cancer drugs." (PMID 29867502, 2018). "CAFs orchestrate the cellular tumorigenic network and contribute to cancer stemness by secreting growth and survival factors such as SDF-1, bFGF, IGF-II and HGF and by inducing the expression of their respective receptors CXCR4, IGF-1R, HGFR." (PMID 28402937, 2017). "To investigate the roles of miR-125b involved in the CXCL12/CXCR4 axis induced EMT, we examined morphologic changes and expression of molecules related to EMT in cancer cells transfected with miR-125b mimics." (PMID 28176874, 2017). "The expression of many genes that induce adhesion, such as CXCR4 and DCN, and cellular movement in cancer, such as DKK1 and ITGB4, evidently increased when FLRT2 was downregulated, and decreased when FLRT2 was upregulated." (PMID 28325946, 2017). "By screening cancer tissue arrays by IHC, we discovered that ACC expresses high levels of CXCR4, and extended these findings using IHC and gene array analyses." (PMID 29088715, 2017). "Cancer cells also typically express molecular markers similar to those expressed in cancer stem cells (CSCs), such as CXC receptor 4 (CXCR4)." (PMID 29228980, 2017). "According to the divergence of CXCR4 expression in different cancers, extensive analyses of CXCR4 expression levels and functional studies will be necessary to understand the precise roles of CXCR4/CXCL12 signaling in different cancer types." (PMID 29020982, 2017). "Collectively, these data suggested that senescent cells work as a ‘storming party' in the collective invasion of cancer through SASP, including MMPs and CXCL12/CXCR4 signalling." (PMID 28489070, 2017). "More importantly, down regulation of CXCR4 and SDF-1α significantly decreased the invasiveness of cancer cells, meaning that expression of CXCR4 is responsible for the cell recruitment." (PMID 28886159, 2017). "The chemokine receptor 4 (CXCR4) and 7 (CXCR7) are G-protein-coupled receptors involved in various diseases including human cancer." (PMID 28945785, 2017). "CNR2 specific agonists (JWH-015 and JWH-133) inhibit growth through different mechanism including inhibition of CXCL12/CXCR4 axis, cyclo-oxygenase-2 (COX-2) expression and induction of apoptosis in different cancer types." (PMID 27213582, 2017). "In the meantime, several CXCR4 antagonists have been synthesized, some of which like AMD3100 (plerixafor) have even been evaluated for their therapeutic potential in cancer patients." (PMID 29163802, 2017). "In summary, our findings suggest that CXCR4 is a potent molecular signaling mechanism in the pathogenesis of CIBP and a potent therapeutic target for cancer pain treatment." (PMID 28638088, 2017). "Co-expression of CXCR4 and ACKR3 has been reported both on separate cells and on the same cells within primary cancers." (PMID 29088715, 2017). "AMD3100 is efficient at inhibiting the proliferation, invasion, and migration of GC cells by attenuating not only the downstream signaling of CXCL12/CXCR4 axis but also interactions between TME and cancer cells." (PMID 28544785, 2017).
cancer (continued). "Less is known about the interference of FHC on CXCR4 signalling in neoplastic cells; to our knowledge this is one of the first reports on the CXCR4-mediated FHC role in cancer." (PMID 28774348, 2017). "The high affinity scFvs bound to receptor CXCR4 and inhibited its ligand, CXCL12, which resulted in cancer cell inhibition." (PMID 28491282, 2017). "More recently, mAbs that target CXCR4 such as LY2624587 and BMS-936564/MDX-1338 have been developed and advanced to clinical studies for cancer treatment." (PMID 29212254, 2017). "CXCR4 and its ligand CXCL12 were present in PanIN lesions and PDAC tissues and demonstrated to result in tumor proliferation, cancer progression, angiogenesis, and metastasis." (PMID 29379802, 2017). "C-X-C chemokine receptor type 4 (CXCR4) is a transmembrane G-protein-coupled receptor which is expressed on cells of the immune system and on cancer cells." (PMID 28356064, 2017). "To rule out the possibility that other cytokines were involved in cancer cell migration, we created two kinds of CXCL12 knockdown senescent cells by shRNA or application of the AMD3100 which is well known CXCR4 antagonist." (PMID 28489070, 2017). "This peptide was more potent than the conventional CXCR4 antagonists (AMD3100 and CTCE-9908) in eradicating the cancer stem cells." (PMID 28196146, 2017). "Several in vitro and in vivo models have revealed a key role of chemokine receptor 4 (CXCR4) and its ligand CXCL12 in the crosstalking between cancer cells and their microenvironment." (PMID 26920352, 2016). "Immunohistochemical staining showed that CXCR4, RhoA, RhoGEF, ARHGAP5, PI3K, ROCK, PAK and PKN were significantly up-regulated in cancer tissues compared with normal tissues." (PMID 27517626, 2016). "Since SDF-1 is an important factor for cancer cell migration to bone marrows, we analyzed the effects of LDE225 on CXCR4, an important chemokine receptor of SDF-1 for MCL homing within the microenvironment." (PMID 26885608, 2016). "In this study, we developed a humanized anti-CXCR4 monoclonal antibody, LY2624587 as a potent CXCR4 antagonist that was advanced into clinical study for cancer." (PMID 26954567, 2016). "Although CXCR4 has been well studied, CXCR6 has also emerged as a major chemokine of interest in cancer." (PMID 26799186, 2016). "A recent meta-analysis also showed higher expression of C-X-C chemokine receptor 4 (CXCR4), another HMGB1′s receptor, indicated poorer prognosis in various types of cancer." (PMID 27391431, 2016). "CXCR4 and its specific ligand, stromal-derived factor 1 (SDF-1), also referred to as CXC ligand 12 (CXCL12), together play a crucial role in cancer survival and metastasis." (PMID 27213454, 2016). "In this study, we explored the potential of PEI-GO in the transfection of siRNAs against CXCR4 (siCXCR4) to suppress the migration of MDA-MB-231 cells, a metastatic cancer cell line overexpressing CXCR4." (PMID 27173676, 2016). "In recent years, significant effort has been invested in the development of small molecule and peptide inhibitors in interrupting the CXCR4 and SDF-1 axis for anti-HIV infection, cancer and other human diseases." (PMID 26954567, 2016). "Chemokine (C-X-C motif) receptor 4 (CXCR4), which is a class-A G protein-coupled receptor (GPCR), has been considered a biomarker for cancer metastasis and poor prognosis." (PMID 27173676, 2016). "Among major immune checkpoints, e.g. PD-1 and CTLA4, the pharmacologic blockage of CXCR4 and its endogenous ligand CXCL12 has appeared as a prime target for blocking strategies in the treatment of cancer patients." (PMID 27462860, 2016). "The aim of the study was to evaluate two putative cancer stem cell markers, CD133 and CXCR4, in the NCI 60 cell lines to identify a cancer stem cell rich population as in vitro models and suggestive for translational studies in patients." (PMID 26020117, 2015).
cancer (continued). "Proteins responsible for this recurrence include the chemokine receptor CXCR4, which is known to enable CRC metastasis, as well as the cancer-initiating cell marker and peptidase CD26, which terminates activity of its chemokine CXCL12." (PMID 26552750, 2015). "Among all known chemokines, CXCR4/CXCL12 has been widely studied and shown to be involved in pathogenesis of several cancers, including LuCa." (PMID 25888629, 2015). "In the last years there is an increasing interest on the interaction of the cancer cells with their microenvironment, mediated by the chemokine ligand CXCL12, and its chemokine receptor 4 (CXCR4)." (PMID 25613038, 2015). "Although the signals generated by the metastatic niche that regulates cancer stem cells are not fully understood, accumulating evidence suggests a key role of the CXCL12/CXCR4 axis." (PMID 26576337, 2015). "Dr-MCsPTX arrested into lung by interacting with endothelium and migrate toward cancer nodule through a complex mechanism involving primarily mouse lung stromal cells (mL-StCs) and SDF-1/CXCR4/CXCR7 axis." (PMID 26264809, 2015). "Some studies have shown that CXCR4 plays a pivotal role in on metastasis of cancer cell, while we found that AFP stimulated CXCR4 expression by activating PI3K/AKT signaling." (PMID 25815363, 2015). "The risk score was accompanied with the downregulation of several cancer-related networks, namely, CXCL12/CXCR4 pathway and JAK/STAT." (PMID 26078947, 2015). "Some studies have successfully shown that blockade of CXCR4 or CXCR4/SDF-1 interactions by siRNA and chemical inhibitors suppressed cancer cell proliferation, invasion and metastasis." (PMID 25753200, 2015). "The CXCR4/CXCR7/CXCL12 chemokine axis has been involved in the progression and organ-specific dissemination of various cancers." (PMID 25955316, 2015). "IL-1β up-regulated the expression of CXCR4, a CXC chemokine receptor that mediates cancer growth and metastasis, at both mRNA and protein levels in Tca8113 TSCC cells." (PMID 26176534, 2015). "In fact, we detected the expression of CXCR4 and/or CXCR7 in cancer cells in the ascites of GC patients and suggested the clinical relevance of these cells by demonstrating their CSC-like features such as a repopulating ability." (PMID 26110809, 2015). "SDF-1 exerts its biological effect by binding and activating the CXC chemokine receptor 4 (CXCR4), a G protein-coupled receptor, which is the predominant receptor for SDF-1 and is frequently overexpressed in a variety of human cancer cells." (PMID 25609203, 2015). "Hypoxia is a prominent regulator of CXCR4 via HIF-1α, and inhibition of HIF-1α decreases the metastasis of cancers." (PMID 26176534, 2015). "The CXCL12-CXCR4 biological axis consisting of the chemotactic factor CXCL12 and its specific receptor CXCR4 plays an important role in cancer metastasis." (PMID 25866764, 2015). "Moreover, CXCR4 may have a role in cancer stem cells in SCCHN." (PMID 26437222, 2015). "While CXCR4 targeted drugs have been developed and are currently in clinical testing, AMD3100 is the only CXCR4 antagonist approved by the FDA for cancer treatment." (PMID 25775124, 2015). "In particular, the chemokine (C-X-C motif) ligand 12 (CXCL12) and its receptors, CXCR4 and CXCR7, have been involved in cancer cell proliferation, migration, and invasion." (PMID 25484899, 2014). "The CXCR4, cell surface receptor for the chemokine CXCL12 (SDF-1), plays a central role in cancer cell proliferation, invasion, and dissemination in the majority of malignant diseases." (PMID 24921652, 2014). "CXCL12 signaling regulates chemotaxis and homing of stem cells to sites of injury, while perturbations of CXCL12 signaling through CXCR4 and/or CXCR7 drive pathogenesis of diseases such as cancer." (PMID 24896823, 2014). "CXCR4-positive cells and CD133/VEGFR-2- double positive cells were observed in the stroma surrounding cancer nests, and VEGF was detected in both cancer and stromal cells." (PMID 24877105, 2014).